EGF (epidermal growth factor)
Diseases named in the same sentence as EGF in open-access papers (continued):
Sharing a sentence is not in itself a finding about the gene and the disease.
cervical carcinoma (85 papers, 2001 to 2026). A carcinoma arising from either the exocervical squamous epithelium or the endocervical glandular epithelium. "Specifically, epidermal growth factor (EGF) treatment of HeLa cervical carcinoma cells caused tTG to localize to leading edges where it catalyzed protein crosslinking events necessary for EGF-stimulated cell motility." (PMID 30344949, 2018). "EGFR activation is a common contributor to malignancy, and many reports have implicated increased EGF signaling as a driver of both ovarian and cervical cancer." (PMID 28640887, 2017). "Since we have also observed that cyclin G2 can exert potent anti-tumorigenic effects, it is possible that inhibition of cyclin G2 by EGFR is a significant event underlying the oncogenic actions of EGF and contributes to ovarian and cervical cancer development." (PMID 28640887, 2017). "Together, our findings demonstrate that CSN6 overexpression can facilitate E6AP stabilization in cervical cancer and provide important insight into the mechanisms underlying EGF pathway deregulation in cervical cancer." (PMID 26318036, 2015). "Epidermal growth factor (EGF) has been shown to be a potent inducer of EMT in cervical cancer and associated with tumor invasion and metastasis." (PMID 23936413, 2013). "Epidermal growth factor (EGF) has been shown to be one of the most potent inducers of EMT in cervical cancer and associated with cervical stromal invasion and nodal metastasis." (PMID 23936413, 2013). "Furthermore, HPV E6/E7 oncoproteins in combination with EGF promote cervical cancer cell proliferation, and HPV E6 causes prolonged tyrosine receptor signaling, resulting in the internalization of phosphorylated receptors, such as EGFR protein." (PMID 36358752, 2022). "EGF functional polymorphism or EGF signaling is involved in influencing cervical cancer prognosis." (PMID 26318036, 2015). "EGF/EGFR signaling events are associated with accelerated tumor progression of cervical cancer." (PMID 23936413, 2013). "The epithelial-mesenchymal transition (EMT) induced by EGF promotes cervical cancer progression; however, the mechanisms underlying the EGF-induced EMT remain unclear." (PMID 23284982, 2012). "In cervical cancer, promoter methylation of EGF was markedly increased in tumor tissues compared to normal controls (normal n = 3; tumor n = 307), implying potential transcriptional silencing via epigenetic repression." (PMID 40692603, 2025). "In serum-starved, quiescent cervical cancer cells, the epidermal growth factor (EGF) triggers polarization and subsequent migration by inducing a redistribution of randomly distributed NHE1 to the simultaneously developing lamellipodia." (PMID 38214759, 2024). "In vitro analysis revealed TF up-regulation by EGF treatment of cervical cancer cells, whereas treatment with cetuximab decreased TF protein levels." (PMID 38719932, 2024). "The desirable characteristics of the hydrogel enable it to soak up liquid in the vicinity of tumors, constantly releasing EGF at minimal levels, helping to prevent tumor growth in a mouse model of cervical cancer." (PMID 39346915, 2024). "In this regard, thermo-responsive PLGA-PEG-PLGA hydrogel has been used for continuous delivery of EGF to prevent recurrence of cervical cancer." (PMID 39346915, 2024). "A redistribution of randomly distributed NHE1, accompanied by the formation of a polarized morphology and the acquisition of the ability to migrate, has been observed in cervical cancer cells upon exposure to EGF." (PMID 38214759, 2024). "Since the proliferation propensity of LY6K‐depleted cervical cancer cells is low, the enhanced EGF signaling pathway was further resolved." (PMID 37076981, 2023). "As a control, we utilized the HeLa cervical cancer cell line stimulated with EGF, which is known to induce C-terminal phosphorylation of ERK5." (PMID 36980305, 2023).
cervical carcinoma (continued). "Several signaling mechanisms for regulating PTGS2 in cervical cancer have been validated, including the EGF and nuclear factor κB (NF-κB) pathways, and PAR2 through an EGFR-dependent mechanism." (PMID 36765810, 2023). "In this study, we explored the effects of LY6K on TGF‐β and EGF signaling pathways in cervical cancer cells." (PMID 37076981, 2023). "Since LY6K depletion affected downstream signals of TGF‐β and EGF, including invasiveness and proliferation of cervical cancer cells, it is possible that LY6K is an important regulator of signal transduction of ligands at the plasma membrane level." (PMID 37076981, 2023). "Early work reported a role for ERK5 in mediating EGF- and serum-induced proliferation in cervical cancer cells." (PMID 36123565, 2022). "EPPK1 is part of the epidermal growth factor (EGF) signaling pathway and promotes cell growth in cervical cancer via the p38 signaling pathway." (PMID 35664780, 2022). "Early work reported that ERK5 mediates serum- and EGF-induced proliferation of cervical cancer HeLa cells, by phosphorylating and promoting transcriptional activation of MEF2C and transcription of c-Jun." (PMID 36123565, 2022). "In the present study, we aim to investigate the effect and safety of intravesical instillation of KFL combined with thrombin and epidermal growth factor (EGF) for radiation-induced HC in patients with cervical cancer." (PMID 33645436, 2021). "Taken together, these data suggest that EGF/HB-EGF-EGFR signalling is required for the proliferative ability of HPV+ cervical cancer cells, and this signalling axis is reduced in cells in which JNK is inhibited." (PMID 33303976, 2021). "This study aimed to assess the effectiveness and safety of intravesical instillation treatment of Kangfuxin liquid (KFL) combined with thrombin and epidermal growth factor (EGF) for radiation-induced hemorrhagic cystitis (HC) in patients with cervical cancer." (PMID 33645436, 2021). "This was a pioneer study done to investigate the effect and safety of intravesical instillation of KFL combined with thrombin and epidermal growth factor (EGF) for radiation-induced HC in patients with cervical cancer." (PMID 33645436, 2021). "Intravesical instillation of KFL combined with thrombin and EGF is an effective and safe therapeutic regimen for radiation-induced HC of grade 2–4 in patients with cervical cancer." (PMID 33645436, 2021). "Taken together, we first reported the intravesical instillation treatment modality using KFL combined with thrombin and EGF for radiation-induced HC of grade 2–4 in patient with cervical cancer." (PMID 33645436, 2021). "Evidence also suggests that PTX3 promotes metastasis of cervical cancer and EGF-induced metastasis of HNSCC through upregulation of MMP-2 and MMP-9." (PMID 34917682, 2021). "All of the cervical cancer cells subjected to EGF treatment expressed more p-ERK1/2, cyclin A1, and c-myc and less p27 (p<0.05), and grew much more quickly (p<0.05)." (PMID 33324557, 2020). "HPV16 E6 is also a target of EGF-induced signaling; its activity was found to be amplified by EGF stimulation in SiHa cervical cancer cells." (PMID 32850421, 2020). "In this study, cell proliferation and invasion were increased under EGF stimulation, and overexpression of miR-125a-5p significantly reversed EGF-induced proliferation and invasion of cervical cancer cell lines." (PMID 32308562, 2020). "In cervical cancer, the epidermal growth factor (EGF) was reported to induce the epithelial-to-mesenchymal transition (EMT), a metastasis-related phenotype that includes cancer cell invasion." (PMID 31235851, 2019). "Here, we identify the coordination among miRNAs and EGF pathway genes which is critical for the maintenance of CSCs in cervical cancer." (PMID 29777148, 2018). "Subsequently, Bcl-3 was found to promote epidermal growth factor (EGF)-induced EMT in cervical cancer cells." (PMID 30200302, 2018).
cervical carcinoma (continued). "While the EGF pathway promotes CSC formation in cervical cancer by inducing SOX2, miR-181a-2-3p/let-7i-5p counteracts the EGF pathway by inhibiting SOX2, thereby reducing the CSC population." (PMID 29777148, 2018). "To study the role of EGFR signaling in cervical cancer cells we stimulated EMT progression with exogenous EGF." (PMID 27902484, 2017). "Our first observation, using single excitation wavelength dual colour FLIM with specifically optimized PKA and ERK1&2 kinase activity reporters, is an EGF-mediated PKA activation concomitant to that of ERK1&2 in the cervical cancer HeLa cell line." (PMID 28106114, 2017). "The depletion of PTX3 inhibited EGF-induced MMP-9, which was consistent with the association between MMP-9 and PTX3 expression observed in cervical cancer cell metastasis." (PMID 28489600, 2017). "In cervical cancer, epidermal growth factor (EGF) has been shown to be a potent inducer of EMT and to be associated with tumor invasion and lymph node metastases." (PMID 27553742, 2016). "Our data show that EGF/Akt signaling is causing the stabilization of E6AP through the Akt-CSN6 axis, which will contribute to carcinogenesis of cervical cancer." (PMID 26318036, 2015). "The chronic treatment of EGF in cervical cancer cells has been shown to increase phosphorylation of glycogen synthase kinase-3 (GSK-3β), a regulator of Snail, thus inducing EMT." (PMID 26356073, 2015). "In cervical cancer, EGF was found to promote lamellipodial stretching by autocrine or paracrine mechanisms, thus promoting cervical cancer cell invasion." (PMID 25295101, 2014). "STIM1-dependent Ca2+ signalings also play an important role in epidermal growth factor (EGF)-stimulated cervical cancer cell migration." (PMID 23594099, 2013). "In cervical cancer, it has been shown that NHE1 up-regulation by EGF is important for cervical cancer cell invasiveness." (PMID 24381558, 2013). "In this study, we found that TACC3 is overexpressed in cervical cancer and can be induced upon EGF stimulation." (PMID 23936413, 2013). "Chronic EGF treatment induces EMT via up-regulation of EMT-inducing transcription factor Snail in cervical cancer cells, and EGF-mediated EMT is correlated with EGF receptor (EGFR) overexpression and clinical progression of cervical cancer." (PMID 23936413, 2013). "EGF has been shown to induce EMT via up-regulation of Snail in cervical cancer cells and activate Akt and ERK signaling pathways." (PMID 23936413, 2013). "Silencing of hSef has further been shown to accelerate EGF-stimulated proliferation of cervical carcinoma cells in vitro." (PMID 19888221, 2009). "We investigated the signalling pathways by which epidermal growth factor (EGF) modulates paclitaxel-induced apoptosis in SiHa human cervical cancer cells." (PMID 11461094, 2001). "High levels of serum EGF and tissue EGF in cervical cancer patients lead to poor prognosis." (PMID 39346915, 2024). "Thus, intravesical instillation of KFL combined with thrombin and EGF is an effective and safe therapeutic regimen for radiation-induced HC of grade 2–4 in patients with cervical cancer." (PMID 33645436, 2021). "However, ZO essential oil was very potent in inhibiting the EGF-stimulated phosphorylation of Akt kinase, which is a crucial kinase to maintain cervical cancer cell survival." (PMID 34371622, 2021). "On the basis of these previous reports, NF-kB may be involved in EGF-induced IL-6 production in HeLa cervical cancer cells." (PMID 31470515, 2019). "Therefore, it is possible that EGF can also regulate the production of IL-6 in HPV18 positive cervical cancer cells through induction of similar signaling pathways." (PMID 31470515, 2019). "Since EGF receptor is frequently over expressed in cervical cancer, we hypothesized that EGF pathway may be responsible for the upregulation of SOX2." (PMID 29777148, 2018).
cervical carcinoma (continued). "However, the expression of PTX3 promotes cervical cancer metastasis and EGF-induced HNSCC metastasis via the up-regulation of MMP-2 and MMP-9." (PMID 28489600, 2017). "We demonstrate that ATXN1 is overexpressed in cervical cancer cells; this overexpression could have been induced by factors such as EGF and that EGF-mediated ATXN1 induction depends on the activation of the EGFR–RAS–MAPK pathway." (PMID 29212253, 2017). "Our results confirm that the EGF pathway is involved in the expression of ATXN1 in cervical cancer." (PMID 29212253, 2017). "We have demonstrated that EGF/EGFR signaling is critical for TACC3-mediated EMT in cervical cancer." (PMID 26356073, 2015). "EGF is also critical in promoting epithelial-mesenchymal transition (EMT) in cervical cancer." (PMID 26318036, 2015). "Our study indicates that PI3K inhibitor in inhibiting Akt and subsequent destabilization of E6AP even under the treatment of EGF may be potential for clinical treatment of cervical cancer patients infected with HPV." (PMID 26318036, 2015). "In our previous studies, we found that ARNT interacted with c-Jun to form c-Jun/ARNT and c-Jun/ARNT/Sp1 complexes which promote expressions of cyclooxygenase (COX)-2, 12(S)-lipoxygenase, and p21WAF1/CIP1, in epidermal growth factor (EGF)-treated cervical cancer cells in a normoxic condition." (PMID 24921657, 2014). "Diverse growth factors, such as EGF, transforming growth factor β (TGF-β) and insulin-like growth factor 1 (IGF-1) have been shown to induce EMT and are significantly associated with the invasiveness, metastasis and recurrence of cervical cancer." (PMID 23936413, 2013). "Collectively, our study highlights a novel function for TACC3 in EGF-mediated EMT process and suggests that targeting of TACC3 may be an attractive strategy to treat cervical cancers driven by EGF/EGFR signaling pathways." (PMID 23936413, 2013). "In this study, we used the human Caski cervical cancer cell line as the model to investigate the role of miR155 in EGF-induced EMT and tried to answer the question of whether miR155 regulates EMT and has a role in metastasis and chemo-sensitivity." (PMID 23284982, 2012). "It has been reported that the EGF receptor is highly elevated in the cervical cancer cells, suggesting that EGF exposure may induce EMT in the cervical cell lines." (PMID 23284982, 2012). "In addition, the treatment with epidermal growth factor of ME180S cervical carcinoma cell line has been found to protect these TNF-α sensitive cells from TNF-α induced apoptosis." (PMID 18257926, 2008). "We hypothesized that this phenotypic heterogeneity reflected corrupted signal transfer in homozygous PIK3CAH1047R iPSCs, including amplification of EGF-dependent responses and increased signaling heterogeneity as observed in HeLa cervical cancer cells with 1 or 2 copies of PIK3CAH1047R." (PMID 39706867, 2025). "Therefore, we hypothesized that autophagy-mediated EGF secretion might induce cisplatin resistance by activating EGFR signaling in cervical cancer." (PMID 37165076, 2023). "Thus, blockade of KCC4 trafficking and surface expression may provide a potential target for preventing IGF-1- or EGF-dependent cervical cancer metastasis." (PMID 35008759, 2021). "We discovered that EGF could induce the phosphorylation of STAT3 in HeLa cervical cancer cells." (PMID 31470515, 2019). "Thus, one could speculate that HPV infection in cervix stimulates cancer stem cell formation via EGF pathway which eventually leads to cervical cancer." (PMID 29777148, 2018). "Therefore, KIAA1199 promotes EGF-induced EMT in cervical cancer cells." (PMID 25366117, 2014). "Moreover, we find a correlation between TACC3 and EGF inducer Snail in cervical cancer." (PMID 23936413, 2013).
cervical carcinoma (continued). "The cytotoxicity of the fusion toxin was clearly target receptor specific because free EGF could effectively block this effect and, moreover, for all the cervical carcinoma cell lines tested, a clear correlation between EGFR expression and sensitivity to the SE fusion toxin could be observed." (PMID 22069572, 2010). "Therefore, we compared the effect of SKI-606 with Iressa, a tyrosine kinase inhibitor (TKI) of EGF and ErbB2 receptors which is presently in phase II clinical trial for patients with recurrent or metastatic cervical carcinomas, in HeLa and SiHa cancer cell lines." (PMID 20862378, 2010). "Inhibiting EGF-induced colony formation and migration in both HPV-positive and HPV-negative cervical cancer cells." (PMID 41608512, 2026). "Our study demonstrates the key role of LY6K in both clathrin‐ and CAV‐1‐mediated endocytic pathways regulated by TGF‐β and EGF, and it suggests a correlation between LY6K overexpression in cervical cancer cells and poor overall survival." (PMID 37076981, 2023). "Since TGF‐β‐ and EGF‐induced proliferation, migration, and invasiveness are affected in LY6K‐depleted cervical cancer cells, the effect of TGF‐β and EGF on signaling pathways was further studied in such cells." (PMID 37076981, 2023). "We therefore investigated the impact of Sorcin on EGF-dependent cell motility in H1299 and Calu-1 NSCLC and in HeLa cervical cancer cells." (PMID 37442828, 2023). "The protein–protein interaction study indicates the interacting partners of EREG, and they were EGF, TGFA, GRB2, and HRAS, and most of them regulate cervical cancer." (PMID 34439555, 2021). "Another study stresses the critical role of KCC4 in the malignant behaviors of cervical cancer cells, especially IGF-1 and epidermal growth factor (EGF) dependent cancer cell invasiveness." (PMID 35008759, 2021). "In the current study, radiation-induced HC of grade 2–4 in patients with cervical cancer received intravesical instillation treatment of KFL combined with thrombin and EGF." (PMID 33645436, 2021). "In the p16-positive cervical carcinoma cell line CERV196, β-catenin levels are increased under epidermal growth factor (EGF) induction, while the expression levels of vimentin and E-cadherin change only slightly, which indicates a pEMT phenotype 42." (PMID 34421348, 2021). "We previously demonstrated that the ethanolic extract of KP, with methoxyflavones as major constituents, exhibited strong anti-cancer activities against HeLa cervical cancer cells by suppressing the MAPK and PI3K/Akt signaling pathways stimulated with EGF." (PMID 31470515, 2019). "Anti-proliferative effects were described in EGF-driven mouse epidermal JB6 Cl41 P+ cells, human cervix carcinoma HeLa and leukemia HL-60 cells." (PMID 31426365, 2019). "Also, EGF receptor (EGFR) is frequently found to be upregulated in cervical cancer and the EGFR amplification is associated with poor prognosis and shorter patient survival, thereby establishing the biological relevance for exploring the significance of EGF in cervical CSCs." (PMID 29777148, 2018). "In conclusion, we have uncovered an intriguing liaison among let-7i-5p, miR-181a-2-3p and EGF/PI3K/SOX2 axis, which is vital for the maintenance of CSCs in cervical cancer." (PMID 29777148, 2018). "For example, epidermal growth factor (EGF)-stimulated cervical cancer cell migration requires STIM1 expression, and the inhibition of SOCE suppresses EGF-induced migration and eliminates extravasation from the vasculature in nasopharyngeal carcinoma cells." (PMID 26919241, 2016). "Our novel findings regarding the EGF/PI3K/AKT/MKRN1 axis leading to PTEN suppression, along with previous data on mutations in ERBB2, and PIK3CA, ultimately indicate that ERBB2- or PIK3CA-targeted drugs might be potential therapeutic treatments for cervical cancers." (PMID 26183061, 2015).